TERT (telomerase reverse transcriptase)
Diseases named in the same sentence as TERT in open-access papers (continued):
Sharing a sentence is not in itself a finding about the gene and the disease.
cystitis (3 papers, 2023 to 2025). Inflammation of the urinary bladder. "Its performance combined with TERT promoter mutation analysis was evaluated in urine of healthy volunteers (n = 50) and patients with cystitis (n = 22) and UBC (n = 70)." (PMID 36831030, 2023). "Among six PDD false-positive samples with the presence of TERT promoter mutations, normal urothelial mucosa was found in one (16.7%), cystitis in three (50%), and others (epithelioid granuloma and papillary urothelial neoplasm of low malignant potential) in two (33.3%)." (PMID 40995307, 2025). "After the implementation of optimal false-positive signal cutoff values, GPR126 and TERT non-coding mutation ddPCR analysis demonstrated the complete absence of tDNA in the control and cystitis groups samples." (PMID 36831030, 2023).
endometriosis (3 papers, 2018 to 2023). The growth of functional endometrial tissue in anatomic sites outside the uterine body. "Cancer cell lines MDA-MB-231, EM-E6/E7/TERT, and endometriosis-related cell lines EEC12Z, iEc-ESCs, and tHESCs showed significantly more invasiveness than the SW1353 cell line (50.3% ± 8%)." (PMID 37371583, 2023). "Increased expression of TERT has been reported in endometriosis from eutopic secretory endometrium and endometriotic lesions." (PMID 37104033, 2023). "When comparing the pattern of invasiveness across all three assays, it is identifiable that the EEC12Z endometriosis cells showed comparably invasive potential to invasive cancer cell lines MDA-MB-231 and EM-E6/E7/TERT." (PMID 37371583, 2023).
fibrosarcoma (3 papers, 2014 to 2025). A malignant mesenchymal fibroblastic neoplasm affecting the soft tissue and bone. "A TERT fusion, likely associated with increased hTERT expression and with poor patient outcome, was identified in a fibrosarcoma sample." (PMID 40711866, 2025).
gastric ulcer (3 papers, 2016 to 2024). An ulcerated lesion in the mucosal surface of the stomach. "High TERT expression in intestinal metaplasia and gastric ulcers have been found, suggesting that over-expression of TERT may act as an early event in gastric carcinogenesis and that detection of TERT could be useful as an early stage marker for the diagnosis of GC." (PMID 27825130, 2016).
Glucose intolerance (3 papers, 2021 to 2025). Glucose intolerance (GI) can be defined as dysglycemia that comprises both prediabetes and diabetes. "Additionally, use of adeno-associated virus serotype 9 (AAV9) vectors to ectopically express TERT in adult mice had beneficial effects such as decreased glucose intolerance, reduced incidence of age-related osteoporosis, improved neuromuscular function, and longevity." (PMID 37707950, 2023). "We have reported that mice lacking TERT in cells of Pdgfrb + lineage (APC‐TERT‐KO) undergo premature APC senescence linked with increased insulin resistance and glucose intolerance." (PMID 39932851, 2025).
heart failure (3 papers, 2016 to 2019). Inability of the heart to pump blood at an adequate rate to meet tissue metabolic requirements. "As the renin angiotensin system is a well characterized contributor to cardiac damage, including remodeling and heart failure, we used Angiotensin II (Ang II) as a systemic stressor to explore the predisposition of TERT knockout rats to external stressors." (PMID 31001540, 2019). "This study demonstrates that functional deletion of TERT predisposes to pathological changes of the heart in function and structure that are consistent with signs of heart failure and decrease functional recovery after an I/R event." (PMID 31001540, 2019). "In the present study, we investigated the role of SIRT6 and TERT in cardiovascular disease in a mouse model of transverse aortic constriction (TAC)-induced heart failure and explored the underlying mechanisms." (PMID 28659816, 2017). "The levels of SIRT6, TERT, and TRF1 were measured in myocardial tissues of mice exposed to TAC or sham surgery to explore the association of sirtuins and telomere function with TAC-induced heart failure." (PMID 28659816, 2017).
idiopathic interstitial pneumonia (3 papers, 2013 to 2023). A class of diffuse lung diseases that typically affect the pulmonary interstitium, although some also have a component affecting the airways (for instance, Cryptogenic organizing pneumonitis). "The telomerase gene TERT, the mucin gene MUC5B, and telomeres have all been linked to idiopathic interstitial pneumonias (IIPs) in genome-wide association studies (GWAS)." (PMID 38203718, 2023). "IPF GWAS performed in Japanese and European individuals have identified genetic risk loci within TERT, TOLLIP/MUC5B, and SPPL2C; a GWAS of the broader phenotype idiopathic interstitial pneumonia identified an association within the MUC5B promoter that was also associated with IPF." (PMID 28774304, 2017).
injury (3 papers, 2021 to 2022). Damage inflicted on the body as the direct or indirect result of an external force, with or without disruption of structural continuity. "STAT3 is a transcription factor that plays a key role in cytokine and growth factor signaling, it has been shown that as a transcription factor of TERT, STAT3 can up‐regulate TERT expression and plays a role in aging and repair nerve injury." (PMID 34262731, 2021). "In intestinal I/R, Nrf2 plays a protective role as it can regulate SLCA11 and HO-1 to limit ferroptosis to attenuate secondary acute lung injury, and can modulate TERT and SLC7A11 to weaken secondary acute liver injury." (PMID 36052333, 2022).
Insulin resistance (3 papers, 2019 to 2025). Increased resistance towards insulin, that is, diminished effectiveness of insulin in reducing blood glucose levels. "Interestingly, changes in TERT expression were negatively correlated to changes in fasting plasma glucose concentrations and in the homeostatic model assessment of insulin resistance." (PMID 31051499, 2019). "Knockout of TERT in fat progenitors, also led to proliferative senescence and AP exhaustion, adipocyte hypertrophy and systemic insulin resistance in male but not female mice, which was aggravated by high fat‐diet." (PMID 34312982, 2021).
intrahepatic bile duct cancer (3 papers, 2021 to 2025). A cancer that involves the intrahepatic bile duct. "The significant association between rs2242652:A in TERT with liver and intrahepatic bile duct carcinoma in the population-based FinnGen cohort and with HCC in the BioBank Japan cohort additionally substantiate this study’s findings." (PMID 35788059, 2023). "In intrahepatic cholangiocarcinoma (ICC), TERT promoter mutations are present in only 5% of cases, with mutation rates falling below 1% in certain populations." (PMID 39871386, 2025).
liver fibrosis (3 papers, 2019 to 2023). "Cholangiocyte-selective deletion of TERT in mice exacerbated fibrosis, whereas androgen therapy toward telomerase rescued liver fibrosis and liver function in a genetic mouse model of PSC." (PMID 37707950, 2023). "Telomerase reverse transcriptase (TERT) was seen in 30–60% of HCCs and molecular studies have shown that genetic aberrations in TERT lead to premature liver fibrosis." (PMID 31366113, 2019).
malaria (3 papers, 2014 to 2025). Malaria is a serious and sometimes fatal disease caused by a parasite that commonly infects a certain type of mosquito which feeds on humans. "We have used the rodent malaria parasite P. berghei because of the high efficiency of transfection and rapid selection of gene-deletion mutants, which might be essential when TERT-deficient parasites show a delayed death phenotype as has been shown for other organisms." (PMID 25275500, 2014). "Genetic studies have demonstrated that TERT is essential for parasite survival, as attempts to knock out the TERT gene in rodent malaria species (P. berghei) resulted in failure to obtain viable clones." (PMID 41001417, 2025). "TERT from human parasites Plasmodium falciparum (malaria) and Toxoplasma gondii (toxoplasmosis) are longer than the TERT of other species." (PMID 29364142, 2018). "This study reports an analysis of telomeres and telomerase of the rodent malaria parasite P. berghei and the unsuccessful attempts to isolate gene-deletion mutants lacking the gene encoding telomerase reverse transcriptase (TERT)." (PMID 25275500, 2014).
malignant phyllodes breast tumor (3 papers, 2021 to 2025). "First, given that TERT promoter hotspot mutations and gene amplification can also be found in MBCs, their detection should be used with caution in the differential diagnosis between MBC and malignant phyllodes tumor of the breast." (PMID 33863915, 2021).
myelodysplastic syndrome (3 papers, 2015 to 2021). A clonal hematopoietic disorder characterized by dysplasia and ineffective hematopoiesis in one or more of the hematopoietic cell lines. "A previous study of mean relative telomere length in familial myelodysplastic syndrome MDS-AML has shown that affected individuals from four small families had shorter telomeres concurrent with mutations in the telomerase gene TERT and its RNA component TERC." (PMID 25351806, 2015). "Indeed, CH rate seems to be lower in individual of Hispanic origin, also confirmed by the lower incidence of myelodysplastic syndromes (MDS) in this ethnicity, while germ-line polymorphisms of the TERT gene seem to be a risk factor." (PMID 33562056, 2021). "Bone marrow failure from AA or myelodysplastic syndrome (MDS) may occur as an isolated manifestation of TBD, most commonly due to TERT or TERC mutations." (PMID 34050178, 2021).
non-melanoma skin carcinoma (3 papers, 2013 to 2021). "On top of 5p15.33 (the locus of CLPTM1L and TERT), prostate and non-melanoma skin cancer also share 6p22.1-p21.31 and 21q22.2-q22.3." (PMID 34290314, 2021). "In summary, our study identifies TERT promoter mutations with a UV-signature as frequent events in BCC and SCC non-melanoma skin cancer." (PMID 24260374, 2013). "Considering that the majority of tumors occurred in our series of SOT recipients included non-melanoma skin cancers, our results suggest that monitoring the circulating TERT mRNA levels could identify SOT patients requiring a more frequent clinical and dermatologic follow-up." (PMID 34746013, 2021). "Moreover, analysis of larger cohorts of SOT recipients developing tumors different from non-melanoma skin cancers is warranted to establish whether circulating TERT mRNA levels can serve as a global early marker of tumor development in this setting." (PMID 34746013, 2021). "Moreover, careful monitoring of circulating TERT mRNA could be helpful in pre-transplantation to define the minimum non-melanoma skin cancer remission times before the graft, due to the high rate of post-transplant relapse in the patients with pre-transplant skin malignancies." (PMID 34746013, 2021).
nonalcoholic fatty liver disease (3 papers, 2017 to 2020). "Rare TERT mutations were also reported in patients with nonalcoholic fatty liver disease (NAFLD)." (PMID 32722302, 2020). "HCC caused by non viral factors, such as alcohol consumption, metabolic syndrome, nonalcoholic fatty liver disease (NAFLD), nonalcoholic steatohepatitis (NASH), hemochromatosis, have a striking high frequency of mutation in TERT promoter." (PMID 28529542, 2017).
osteoporosis (3 papers, 2020 to 2023). A condition of reduced bone mass, with decreased cortical thickness and a decrease in the number and size of the trabeculae of cancellous bone (but normal chemical composition), resulting in increased fracture incidence. "Decreased TERT activity and reduced osteogenic capacity in aging-related diseases such as osteoporosis caused by aging and sex hormone deficiency, as well as the positive effect of telomerase gene therapy on osteoporosis, have been reported." (PMID 37862118, 2023). "TERT gene knockout decreased the osteogenic ability of BMMSCs and osteoblasts significantly, and accelerated cell ageing, but did not affect the function of osteoclasts, resulting in loss of bone mass and osteoporosis." (PMID 33210341, 2021). "In summary, our experiments confirmed that the GSK3β/β-catenin/TERT pathway could regulate the osteogenic differentiation and apoptosis of BMSCs and that TERT might be a promising target for the future treatment of osteoporosis." (PMID 37862118, 2023). "Our experiments confirmed the promoting effects of TERT on osteogenic differentiation and the inhibitory effects on apoptosis of BMSCs both in vitro and in vivo, providing a new idea for the future treatment of osteoporosis." (PMID 37862118, 2023). "TERT might serve as a new therapeutic target in osteoporosis." (PMID 37862118, 2023). "Therefore, this experiment focused on the role of TERT in regulating osteogenic differentiation, apoptosis, and the development of osteoporosis in BMSCs and whether the Wnt pathway has a regulatory effect on TERT." (PMID 37862118, 2023). "The biological functions of TERT, β-catenin, and GSK3β in osteoporosis and the effects of LiCl on their expression have not been explored." (PMID 37862118, 2023).
penile carcinoma (3 papers, 2021 to 2023). "Thereby, it is possible to conclude that TERT promoter mutations in penile carcinoma precedes the occurrence of other oncogenic mutations." (PMID 38033865, 2023). "The search for TERT promoter mutations in penile carcinoma showed an overall prevalence above 50%, which was significantly higher in HPV negative cases (>65%)." (PMID 38033865, 2023). "TERT mutations were described in a high frequency of penile carcinomas, especially in the non-HPV related subtypes." (PMID 36564761, 2022). "We speculate that in HPV-related penile SCC, telomerase is activated by HPV E6 in the absence of TERT-p mutation, whereas mutations of TERT-p might play a role in the mechanism of telomerase activation in non-HPV-related penile cancer." (PMID 33635430, 2021).
pituitary tumor (3 papers, 2020 to 2025). A benign or malignant neoplasm affecting the pituitary gland. "Aberrant TERT promoter methylation is associated with TERT upregulation in malignancies and shorter progression-free survival and tumor recurrence in pituitary tumors." (PMID 32201880, 2020). "TERT was examined, but no specific pathogenic role was identified in pituitary tumors." (PMID 39859246, 2025).
pneumonia (3 papers, 2017 to 2023). An acute, acute and chronic, or chronic inflammation focally or diffusely affecting the lung parenchyma, caused by an infection in one or both of the lungs (by bacteria, viruses, fungi, or mycoplasma.). "Nevertheless, it is still meaningful to analyze the combined impact of different variants of other genes [e.g., rs2736100 in TERT (telomerase reverse transcriptase)] on the susceptibility to the different types of pneumonia in different populations when the data become available." (PMID 32252656, 2020).
prostate tumors (3 papers, 2017 to 2022). "Comparing the TF frequencies in the models of tumors and healthy controls led to a list of 17 significant TF predicted to regulate TERT specifically in prostate tumors." (PMID 35267575, 2022). "TERT expressions showed an elevated trend in metastasis prostate tumors in several independent cohorts of PCa even though the significance was not strong in Taylor and Yu datasets." (PMID 34858826, 2021).
retinoblastoma (3 papers, 2013 to 2025). A malignant tumor that originates in the nuclear layer of the retina. "We used mouse embryonic fibroblasts (MEFs) as normal diploid control for mouse retinoblastoma and TERT-immortalized human fibroblasts (BJ) as a diploid control for human retinoblastoma." (PMID 23765217, 2013).
Sepsis (3 papers, 2020 to 2024). Sepsis is defined as life-threatening organ dysfunction caused by a dysregulated host response to infection. "The present study revealed that TERT maintains cell stability during the acute phase (D3) of sepsis induced by LPS, but it also stimulates inflammation by stimulating NF-κB." (PMID 33819185, 2021). "Additionally, results in the present study suggested that overexpression of TERT led to increased inflammation in the acute phase of sepsis induced by LPS, and higher TERT level at convalescent phase promoted cell proliferation and reduced abnormal cell apoptosis, thus increasing the recovery rate." (PMID 33819185, 2021). "The expression of catalytic TERT remained unchanged across the cell types and groups, whereas TERC expression was significantly upregulated in the CD4+ T cells of sepsis patients (* p < 0.05)." (PMID 32825352, 2020).
spitzoid melanoma (3 papers, 2015 to 2025). "TERT promoter mutations can stratify clinical risk for patients with Spitzoid melanoma, but the application of TERT promoter mutations detection for risk stratification in clinical practice still needs large-scale verification." (PMID 35903534, 2022). "The results showed that the presence of TERT promoter mutations was significantly related to the risk of extra lymph node metastasis or death from Spitzoid melanoma." (PMID 35903534, 2022). "Spitzoid melanomas often have kinase fusion gene alterations such as ALK, NTRK and ROS1, but when TERT promoter mutations are found, they may be a marker of a more aggressive behaviour." (PMID 40926920, 2025).
synovial sarcoma (3 papers, 2014 to 2021). "Finally, a TERT promoter mutation at position C228T was found in one of the synovial sarcomas (SSs) examined (1/25; 4%)." (PMID 24726063, 2014).
tongue cancer (3 papers, 2016 to 2026). A malignant neoplasm affecting the tongue. "Notably, tongue cancers in women are reported to exhibit distinct genetic alterations, such as TERT promoter and MYH9 mutations, suggesting that female tongue cancers are clinically and biologically distinct." (PMID 41549073, 2026). "Red rectangles represent the hit genes involved in the treatment of tongue cancer (TERT, Bcl-2, CDK4/6, CDK2, VEGF, ER, RXR,c-KIT, MET, FGFR, PPAR8, PFFP, MMPs, CDK4, AR, F2, IGFR)." (PMID 39863836, 2025). "Only a single cell was noticed growing in soft agar in the culture of TERT-SHED P20, while cell aggregates were formed in the culture of tongue cancer cells (Tca-8113)." (PMID 27044500, 2016).
tongue squamous cell carcinoma (3 papers, 2017 to 2022). A squamous cell carcinoma that arises from the tongue. "Actually, a previous study also has demonstrated that BMAL1 transcriptionally down-regulates its downstream target TERT in an EZH2-dependent manner in tongue squamous cell carcinoma cells." (PMID 36439870, 2022). "BMAL1 also increases sensitivity to paclitaxel in tongue squamous cell carcinoma by recruiting enhancer of zeste homolog 2 (EZH2) repressors to the telomerase reverse transcriptase (TERT) promoter to prohibit TERT transcription." (PMID 32231148, 2020).
ureter carcinoma (3 papers, 2014 to 2021). A carcinoma that arises from epithelial cells of the ureter. "In 14 UTUC tumor specimens, the sequencing result revealed TERT promoter mutations in 3/5 (60%) renal pelvic cancer and 1/9 (11%) ureter cancer, and all of them were C228T mutations." (PMID 24742867, 2014).